GARS1-DT (GARS1 divergent transcript)
Synonyms: AC005154.6; AC005154.1; formerly GARS-DT
Gene: Long non-coding RNA gene on chromosome 7 (30,516,309 to 30,595,286, reverse strand). Ensembl gene ENSG00000196295.
Diseases named in the same sentence as GARS1-DT in open-access papers:
GARS1-DT is named in the same sentence as 1 disease in open-access papers, as found by Europe PMC text mining. Sharing a sentence is not in itself a finding about the gene and the disease.
GARS1-DT shares sentences with these, for which no sentence is quoted: cancer (1 paper).